FLT1 (fms related receptor tyrosine kinase 1)
Diseases named in the same sentence as FLT1 in open-access papers (continued):
Sharing a sentence is not in itself a finding about the gene and the disease.
preeclampsia (continued). "Thus, gestational age mismatch may potentially explain some of the differences in the levels of vesicle-associated Flt-1 observed in severe preeclampsia." (PMID 28790977, 2017). "Thus, it is crucial to characterize the orientation and function of Flt-1 directly in PE micro- and nano-vesicles in order to definitively determine whether vesicle-associated Flt-1 play any role in the pathogenesis of preeclampsia." (PMID 28790977, 2017). "In view of the possible role of the Flt-1 gene in the etiology of preeclampsia, we investigated whether the dinucleotide (threonine-glycine; TG)n repeat polymorphism in the 3' non-coding region of the Flt-1 gene is associated with preeclampsia in Korean pregnant women." (PMID 18631405, 2008). "While the FLT1 gene exhibited less pronounced differences between groups, a subtle decrease in upstream coverage was observed in the preeclampsia cases compared to controls." (PMID 40061129, 2025). "Soluble Flt-1 is encoded by an alternatively spliced transcript of sFlt-1 is an antagonist of VEGF and PIGF and is up-regulated in preeclampsia." (PMID 38910142, 2025). "As Flt-1 (vascular endothelial factor receptor 1) is to some extent alternatively spliced, thus leading to soluble forms pathogenically relevant to preeclampsia, we assessed its expression in response to NaCl." (PMID 38966986, 2024). "Specific markers, such as elevated liver function tests, thrombocytopenia, FDA-approved ratio of soluble Fms-like tyrosine kinase 1 (s-Flt-1) over placental growth factor (PIGF) can aid in distinguishing preeclampsia from CKD progression." (PMID 39627749, 2024). "Seven genes (including MKNK1, ARNT, FLT1, SERPINE1, ENO3, LDHA, BCL2) were screen out to build potential diagnostic model of preeclampsia." (PMID 37020283, 2023). "FLT1 expression in the blood samples of patients with preeclampsia was higher than that in control patients, but the difference was not significant." (PMID 37389124, 2023). "In the cell type-naïve differential expression model, consistent with previous findings, placentas from pregnancies with preeclampsia overexpressed FLT1, LEP, and ENG59–62." (PMID 36914823, 2023). "FLT1 encodes Fms-related tyrosine kinase 1 (FLT1 or VEGFR1), which is related to reactive oxygen species, and sFlt1, the soluble form of FLT1, is widely used for diagnosis and management in preeclampsia with placental growth factor (PIGF)." (PMID 37020283, 2023). "In the present study, FLT1 expression was significantly increased in the placentas of patients with preeclampsia." (PMID 37389124, 2023). "FLT1 levels in the placenta of patients with preeclampsia were significantly upregulated (p = 0.014)." (PMID 37389124, 2023). "In white women, FLT1 rs722503, FLT4 rs307826, and VEGFC rs7664413 were significantly associated with preeclampsia." (PMID 36901702, 2023). "The distinct upregulation of COL17A1, SERPINA3, FSTL3, and FLT1 in preeclampsia was further demonstrated." (PMID 35528613, 2022). "The FLT1 gene is well known to express a soluble isoform (sFLT-1) that can tightly bind VEGF and suppress angiogenic activity and is associated with preeclampsia." (PMID 35562897, 2022). "COL17A1, FLT1, FSTL3, and SERPINA3 were identified as diagnostic genes of preeclampsia and validated in the GSE44711 datasets." (PMID 35528613, 2022). "Our study identified COL17A1, FLT1, FSTL3, and SERPINA3 as novel diagnostic biomarkers for preeclampsia patients." (PMID 35528613, 2022). "The FLT1 gene contains 30 exons with 5 isoforms (9 isoforms in GRCh38) and has also been shown to be involved in preeclampsia." (PMID 35562897, 2022). "A high level of soluble flt-1 was secreted in severe preeclampsia, which neutralized the effect of PIGF and VEGF." (PMID 36420291, 2022). "The link between Flt1 protein levels and reduced Vegfa/Vegfr signalling provides a well-known mechanism for vessel rarefaction and hypertension, for example in preeclampsia." (PMID 35312765, 2022).
preeclampsia (continued). "ADAM10 has also been shown to mediate the release of the soluble Flt-1 isoform, a known marker of preeclampsia and knockdown of ADAM10 leads to decreased sFlt-1." (PMID 35562897, 2022). "The most interesting gene in this respect is FLT1, well known for its differential transcript usage in preeclampsia, where soluble transcripts of the gene are highly increased in preeclamptic pregnancies." (PMID 34095140, 2021). "Increased Flt1 and Eng transcripts as well as proteins were observed in placenta of preterm preeclampsia that can dysregulate angiogenesis leaving placental tissue and embryonic tissues in state of hypoxia." (PMID 34195300, 2021). "In this study, we found that autophagy is repressed, trophoblast apoptosis is enhanced (Bax was upregulated), and angiogenesis is impaired (VEGFA was downregulated, and FLT1 was upregulated) in preeclampsia." (PMID 34568425, 2021). "Evidence suggests that the pathogenesis of preeclampsia is initiated by placental ischemia, followed by release of placental anti-angiogenic factors like soluble Flt-1 (sFlt-1) and soluble endoglin (sEng) into the circulation." (PMID 31443707, 2019). "The most promising foetal and placental biomarkers for identifying preeclampsia are placental growth factor (PlGF) and soluble Flt-1 (sFlt-1), which are discussed subsequently." (PMID 31590294, 2019). "To date, several studies have demonstrated that circulating soluble Flt-1 is a useful marker for diagnosis and prediction of preeclampsia, combined with placental growth factor level." (PMID 29937525, 2018). "A candidate gene approach has discovered about 70 genes to be associated with preeclampsia and some of the genes overlap with the breast cancer susceptibility genes such as ACE, VEGF, IGF1R and FLT1." (PMID 29361985, 2018). "In early-onset preeclampsia, biomarkers such as FLT-1, ICAM (intercellular adhesion molecule 1), and NAD(P)H (nicotinamide adenine dinucleotide phosphate) oxidase are increased compared in late-onset preeclampsia." (PMID 30363976, 2018). "Soluble endoglin has been reported to be involved in the pathogenesis of preeclampsia together with soluble Flt-1." (PMID 29937525, 2018). "Two percent O2 induced the dysregulation of only five genes, including LEP and FLT1, from the set of genes investigated in the placenta in preterm preeclampsia, while alternating O2 concentrations induced the dysregulation of only three genes." (PMID 30135684, 2018). "In module M2, FLT1, which expresses sFlt-1, the main driver of BP elevation in the terminal pathway of preeclampsia, was up-regulated." (PMID 30135684, 2018). "Circulating soluble Flt-1 was demonstrated to be increased in patients with preeclampsia, and to be related to decreased blood levels of VEGF-A, leading to glomerular endothelial injury." (PMID 29937525, 2018). "Micro- and nano-vesicles extruded by human placentae carry Flt-1 across gestation and in severe preeclampsia, the levels of vesicle-bound Flt-1 are upregulated." (PMID 28790977, 2017). "Later hsFlt-1-e15a expression was found to be up-regulated in the trophoblast by hypoxia, and hsFlt-1-e15a isoform to be the most abundant sFlt-1 isoform in the placenta in women with preeclampsia, corresponding to 81.69% of the FLT1 transcripts." (PMID 25860260, 2015). "Alternative splicing of the VEGFR-1 (FLT1) gene produces the soluble form and the role of sFlt1 in preeclampsia is further complicated by the existence of multiple splice variants of sFlt1." (PMID 26042465, 2015). "To investigate this, we first assessed the expression of the two most frequently studied markers of preeclampsia, soluble FLT1 (sFLT1) and soluble ENG (sENG), produced in the placenta and found elevated in the maternal serum early in pregnancy." (PMID 25679511, 2015). "We confirmed several placenta proteins, such as Flt-1 and Endoglin, known to be changed in preeclampsia." (PMID 25392996, 2014).
preeclampsia (continued). "Our findings in HUVEC suggested the same downstream effects on the gene signature for GTF2E1 inhibition as that of FLT1 (i.e., a molecular mediator of preeclampsia symptoms) inhibition with the altered gene signature mimicking preeclampsia development." (PMID 24885447, 2014). "Macrophages regulate angiogenesis by secreting VEGF, which binds to fms-like tyrosine kinase-1 (Flt-1), both of which are dysregulated in preeclampsia." (PMID 25566263, 2014). "On the other hand, four proteins (Endoglin, Nox4, Flt-1 and Calretinin) were positively correlated and two proteins (AnnexinXI and PlGF) were inversely correlated with the severity of term preeclampsia (P<0.05, R value≥0.4)." (PMID 25392996, 2014). "FLT1 had been identified as a molecular mediator of clinical symptoms of preeclampsia in previous studies." (PMID 24885447, 2014). "The results showed that Flt-1, PAI-1, PBEF and PSM were strongly associated with adverse outcomes in patients with preterm preeclampsia." (PMID 25392996, 2014). "In the preeclampsia setting, low serum VEGF levels combined with elevated levels of VEGF inhibitors, such as soluble FLT-1 and soluble endoglin (sEng), cause cerebral endothelial damage and symptoms of PRES." (PMID 23243534, 2012). "From these 18 microarray studies in preeclampsia, the most repeatedly reported genes are fms-like tyrosine kinase 1 (FLT1) and endoglin (ENG)." (PMID 22929622, 2012). "Enhanced expression of the FLT1 gene in preeclamptic placenta is consistent with the observation that sFlt1 is increased in the maternal circulation in women destined to develop preeclampsia." (PMID 22929622, 2012). "It has been established that VEGF-B primarily interacts with Flt-1 (vascular endothelial growth factor receptor) and sFlt-1 (soluble vascular endothelial growth factor receptor-2) and inhibits vascular endothelial dysfunction in preeclampsia." (PMID 39861168, 2025). "This trend suggests a potential shift towards a more open chromatin configuration in preeclampsia, which may contribute to the later observed increase in FLT1 expression." (PMID 40061129, 2025). "In summary, our study identified MKNK1, ARNT, FLT1, SERPINE1, ENO3, LDHA, BCL2 out of HIF1-signaling pathway as novel diagnostic biomarkers for preeclampsia patients, and a diagnostic signature based on these genes is constructed for preeclampsia." (PMID 37020283, 2023). "Therefore, it is possible that very high maternal soluble Flt-1 levels are required for preeclampsia to develop." (PMID 36674486, 2023). "The FLT1 protein (also known as VEGFR1), which plays an essential role in the development of embryonic vasculature and angiogenesis, has primarily been suggested as a biomarker for early-onset preeclampsia and fetal growth restriction." (PMID 37958809, 2023). "However, there was good evidence from other studies that demonstrated an increased level of flt-1 in preeclampsia, which led to decreased circulating free VEGF." (PMID 36420291, 2022). "It showed that changes near the fms-like tyrosine kinase 1 (FLT1) site in the human fetal genome could contribute to preeclampsia." (PMID 35669649, 2022). "Besides confirming increased levels of Flt1 and Eng in preeclampsia, we also observed an increase in various mediators of maternal inflammation in women with PPE compared to preterm cohort." (PMID 34195300, 2021). "Soluble Flt-1 (sFlt-1) is a protein whose values are elevated in preeclampsia and may continue to be high during postpartum in women with a preeclampsia diagnosis." (PMID 34944543, 2021). "We confirmed that autophagy-related genes (LC3B and Beclin1) and VEGFA were downregulated, while Bax and FLT1 were upregulated in placentas from preeclamptic women, indicating that the autophagy pathway might play a significant role in preeclampsia." (PMID 34568425, 2021).
preeclampsia (continued). "Several studies have validated the hypothesis that preeclampsia arises due to ‘increase in the level of endogenous soluble Flt-1 (sFlt-1) that may antagonize the beneficial effects of vascular endothelial growth factor (VEGF)’." (PMID 33137710, 2021). "For example,showed that long non-coding RNA nucleus-rich transcript 1 (NEAT1) could inhibit trophoblast proliferation in preeclampsia rats through the microRNA-373/Fms related receptor tyrosine kinase 1 (FLT1) axis." (PMID 33967782, 2021). "Analysis also showed that the s-Flt-1/PlGF ratio at baseline, as investigated in other conditions such as preeclampsia, may provide additional help." (PMID 34871241, 2021). "Soluble Flt-1 (sFlt-1) is elevated in preeclampsia and may remain high postpartum in women with a history of preeclampsia." (PMID 32660064, 2020). "The risk allele of the FLT1 variant did not associate with increased risk in gestational hypertension offspring (P = 0.21)." (PMID 33239696, 2020). "In the last decade, the hypothesis that preeclampsia arises due to “increase in the level of endogenous soluble Flt-1 (sFlt-1) that may antagonize the beneficial effects of vascular endothelial growth factor (VEGF)” has been validated." (PMID 32660064, 2020). "Hence, further research into the cooperative transcription factors engaged in hypoxia-induced up-regulation of Flt-1 gene expression in trophoblasts is necessary to elucidate the mechanism of Flt-1 gene transcriptional activation in preeclampsia." (PMID 30478339, 2018). "These lists contain many candidates known to be involved in the pathophysiology of FGR, such as Flt-1 and LEP, which have been described in up to one third of the studies using placentas derived from pregnancies complicated by preeclampsia, a placental disorder frequently associated with FGR." (PMID 29983832, 2018). "Whether different size fractions of EVs carry Flt-1 in preeclampsia and can activate endothelial cells through a Flt-1-mediated mechanism was also investigated." (PMID 28790977, 2017). "We investigated whether placental EV production is altered in preeclampsia such that they induce endothelial cell activation, and whether (s)Flt-1 is involved." (PMID 28790977, 2017). "Since placental micro- and nano-vesicles carry Flt-1 from the first trimester onward, placental EVs may be one placental toxin/danger signal that contributes to the pathogenesis of preeclampsia, partially in a Flt-1-dependent manner." (PMID 28790977, 2017). "It is interesting to speculate that the different distribution patterns of placental EVs, and therefore vesicle-bound Flt-1, in vivo may contribute to the wide variety of organ-specific symptoms observed between different women with preeclampsia." (PMID 28790977, 2017). "A possible explanation for the increase in Flt-1 seen in preeclamptic placentas, particularly in early-onset preeclampsia may be related to the early events in gestation that occur in preeclampsia." (PMID 27315098, 2016). "Most of studies except a few studies showed up-regulation of Flt1 mRNA in preeclampsia." (PMID 26221124, 2015). "Studying about Flt1 gene regulation and its splicing may help for better understanding of preeclampsia pathogenesis and lead to prevention and treatment of the disease." (PMID 26221124, 2015). "However, the finding that vascular endothelial growth factor (VEGF) stimulates nitric oxide release from trophoblasts and endothelial cells via the VEGF receptor-1 (Flt-1) has led to a new approach to tackling preeclampsia." (PMID 24503248, 2014). "Furthermore, the expression levels of some of these proteins correlated with neonatal small for gestational age (PAI-1 and PAPP-A) and adverse outcomes (Flt-1) in women with preterm preeclampsia." (PMID 25392996, 2014). "Basic research has shown that genetic events play a major role in the development of preeclampsia, particularly, the gene of fms-like tyrosine kinase 1(Flt-1), which might be one of the important genetic events in preeclampsia." (PMID 24312300, 2013).
preeclampsia (continued). "In this study, we tested, for the first time, the association between preeclampsia and the TG dinucleotide repeat polymorphism in the 3' non-coding region of the Flt-1 gene." (PMID 18631405, 2008). "The pattern of elevated FLT1 with reduced VEGF and PlGF could create a functionally anti-angiogenic environment by sequestering free ligand, analogous to mechanisms implicated in preeclampsia." (PMID 41393147, 2025). "From the molecular point of view, preeclampsia is associated with the upregulation of circulating levels of anti-angiogenic factors soluble Flt-1 (sFlt-1) and soluble endoglin that might account for maternal vascular dysfunction and oxidative stress described in preeclampsia." (PMID 34196872, 2021). "Data offered a link between ACE2 downregulation and an AngII/s-Flt-1-mediated endothelial dysfunction in a model that strictly resembles preeclampsia, which could offer an explanation to the pathogenesis of the acute global vascular damage observed in these patients." (PMID 34208017, 2021). "It is well known that preeclampsia is closely associated with placental dysfunction characterized by altered maternal and placental levels of angiogenic factors like vascular endothelial growth factor (VEGF) and placental growth factor (PlGF) and its receptors fms-like tyrosine kinase-1 (Flt-1)." (PMID 31443707, 2019). "In addition to preeclampsia, soluble Flt-1 may affect the process of various kidney diseases through antagonizing VEGF-A." (PMID 29937525, 2018). "Flt-1 misregulation in peripheral blood mononuclear cells of pregnant women can result in the over-expression of sFlt-1, which may produce an additional (extra-placental) source of sFlt-1 that contributes to the etiology of preeclampsia." (PMID 18631405, 2008). "In the present study, we screened LEP, FLT1, RAB6C, and SASH1 as potential biomarkers for preeclampsia." (PMID 37389124, 2023). "A substantial proportion of the overexpression of the FLT1, LEP, and ENG in preeclampsia was mediated by placental cell composition." (PMID 36914823, 2023). "We identified characteristic genes of preeclampsia as LEP, FLT1, RAB6C, and SASH1 using the GEO database and verified them using the GSE160888 and GSE96985 datasets." (PMID 37389124, 2023). "Finally, to quantify the attenuation of differential expression of the preeclampsia biomarkers FLT1, LEP, and ENG, we applied mediation analysis to show cellular composition mediated a substantial proportion of the association between preeclampsia and FLT1, LEP, and ENG overexpression." (PMID 36914823, 2023). "In fact, soluble FLT1 and ENG antagonizes VEGF binding to its receptor contributing to hypertension, proteinuria and endothelial cell dysfunction in preeclampsia." (PMID 35943095, 2022). "In summary, these analyses de novo re-identified a known factor of preeclampsia and IUGR, alternative splicing of FLT1, which validates the approach, and found hundreds of other disease-associated genes that are affected by splicing." (PMID 33433680, 2021). "Administration of both soluble FLT1 and ENG in pregnant rats produces a severe preeclampsia-like symptom with hypertension, proteinuria, glomerular endotheliosis, and thrombocytopenia." (PMID 32566660, 2020). "In the “BCL6-ARNT2” pathway, which is activated only in preterm preeclampsia, ischemic stress of the trophoblast coupled with BCL6 and ARNT2 overexpression increases FLT1 expression." (PMID 30135684, 2018). "There were 9 genes (6 in the M2 and 3 in the M1 modules) dysregulated in BeWo cells, including FLT1, ARNT2, and ZNF554, similar to preeclampsia." (PMID 30135684, 2018).